HMGB1 (high mobility group box 1)
Diseases named in the same sentence as HMGB1 in open-access papers (continued):
Sharing a sentence is not in itself a finding about the gene and the disease.
Sepsis (continued). "Treatment of CLP-induced sepsis with anti-HMGB1 pAb however, left these mice with significantly higher survival rates after secondary bacterial challenge than either control groups." (PMID 28724977, 2017). "High-mobility group box (HMGB1) is a cytokine identified as a late mediator of sepsis and that plays a critical role in endothelial cell barrier disruption by rearranging the actin cytoskeleton into a contractile phenotype." (PMID 29258263, 2017). "Here, we found increased serum IL-6, CXCL1, and HMGB1 levels in sepsis survivors 2 weeks post-CLP when compared to sham controls." (PMID 29326685, 2017). "Measurements of other biomarkers e.g. nuclear protein high mobility group box protein 1 (HMGB1) has emerged in sepsis, and we cannot exclude other biomarkers to link to survival in our model." (PMID 29204105, 2017). "IL8, IL15 and HMGB1 were significantly up regulated in other sepsis cases compared to healthy controls." (PMID 28628607, 2017). "It acts as one of specific antagonists of HMGB1, and plays a protective role in sepsis by attenuating excessive inflammation." (PMID 29190939, 2017). "Taken together, these results suggest that ovine anti-HMGB1 pAb can increase survival from acute and rapid severe systemic inflammation induced by LPS in this lethal and highly artificial model of sepsis." (PMID 28724977, 2017). "Following this discovery, the cytokine role of HMGB1 has been further confirmed in numerous studies linking to diseases such as sepsis, lung disease, arthritis, stroke and haemorrhagic shock." (PMID 28067797, 2017). "In murine sepsis survivors, proinflammatory signaling induced by HMGB1 mediates cognitive deterioration." (PMID 29326685, 2017). "When sepsis occurs, various types of cells are damaged, and then HMGB1 is then passively released from the nucleus of the necrotic cells." (PMID 28947753, 2017). "Our findings provide direct evidence of HMGB1 expression in brain tissues, and show its potential role in sepsis induced brain injury." (PMID 29190939, 2017). "Inhibition of HMGB1 secretion attenuates systemic inflammatory response syndrome and sepsis-induced organ injury." (PMID 28931916, 2017). "Nucleocytoplasmic HMGB1 translocation increases in acute lung injury, and the inhibition of HMGB1 secretion attenuates systemic inflammatory response syndrome and sepsis-induced organ injury." (PMID 28931916, 2017). "In vivo, we detected the inhibitory effects of salidroside on HMGB1 release and lung injury by creating a rat model of sepsis." (PMID 29333216, 2017). "In our study, the treatment with paricalcitol in mouse model of LPS-induced sepsis increased the survival rate of mice and decreased the LPS-induced HMGB1 secretion in serum." (PMID 29085368, 2017). "The present study shows for the first time the mechanism by which C. longa ameliorates sepsis, namely, by suppressing NO signaling and thereby inhibiting the release of the proinflammatory cytokine HMGB1." (PMID 28929026, 2017). "Activation of NLRs and RLRs promote the assembly of inflammasomes 14 which mediate the release of inflammatory cytokines including TNF‐α, IL‐1, IL‐6, IL‐18, and HMGB1, which itself also possesses an inflammatory cytokine function in sepsis." (PMID 28186706, 2017). "Our findings clearly demonstrated that excessive release of HMGB1 contributes to the development of immune dysfunction in sepsis." (PMID 28947753, 2017). "Growing evidences suggest that HMGB1 plays an important role in inflammatory diseases such as sepsis." (PMID 29333216, 2017). "HMGB1, a ubiquitous DNA-binding protein, has been identified as a critical late mediator in endotoxaemia and sepsis." (PMID 29333216, 2017). "Nevertheless, antagonizing brain HMGB1 didn't significantly reverse the high mortality rate induced by severe sepsis in our study." (PMID 29190939, 2017). "We used a CLP model of sepsis and in vitro LPS or HMGB1-treated NR8383 cells to examine the effects of GL on expression of HMGB1 and proinflammatory cytokines." (PMID 28484719, 2017).
Sepsis (continued). "Taken together, these results suggest anti-HMGB1 pAb treatment improves survival from secondary infection following CLP-induced sepsis, potentially via alterations in cytokine responses." (PMID 28724977, 2017). "HMGB1 contributes to renal ischemia-reperfusion injury, sepsis-induced kidney injury, and severe acute pancreatitis-related kidney injury." (PMID 28694564, 2017). "The first information about HMGB1 activity has been collected in models of sepsis and systemic infections; the idea that this alarmin is involved in the sterile inflammation and fibrosis rapidly increased and fibrosis." (PMID 29200665, 2017). "The proinflammatory activity of HMGB1 was first demonstrated in a sepsis mouse model as a late mediator of lethality, in which HMGB1 is actively secreted by activated macrophages." (PMID 28403838, 2017). "Findings from both animal models with sepsis and septic patients have shown a delayed elevation of serum HMGB-1 levels." (PMID 28286376, 2017). "In comparison with the sham group, HMGB1 protein levels of various brain regions were all significantly elevated in the sepsis group, as shown by immunofluorescence results." (PMID 29190939, 2017). "Serum HMGB1 concentration was markedly elevated from 8 to 36 hours, and accounted for high mortality rate of severe sepsis." (PMID 29190939, 2017). "It was also shown evidence of enhanced HMGB1 expression by Western blotting in the setting of sepsis." (PMID 29190939, 2017). "Extracellular HMGB1 is a late mediator of sepsis and acts as a key regulator in acute and chronic inflammation." (PMID 28931916, 2017). "Previous studies suggested HMGB-1 levels increase earlier (less than an hour after injury) in trauma or haemorrhagic shock patients than those with sepsis." (PMID 28286376, 2017). "In particular, macrophage-derived HMGB1 was found to mediate lethal LPS-induced sepsis in mice: this function occurred late after LPS administration." (PMID 28929026, 2017). "Sepsis increased NF-κB activation and HMGB1 nucleocytoplasmic translocation and iNOS protein expression, but decreased SIRT1 protein expression in lung tissues." (PMID 28931916, 2017). "In order to determine the effect of HMGB1 neutralisation on the inflammatory profile in CLP-induced sepsis, serum samples were obtained on day 1, 3, and 7 post surgery and assessed for levels of pro- and anti-inflammatory cytokines." (PMID 28724977, 2017). "HMGB1 is an important mediator of the inflammatory response which is always exaggerated in sepsis and contributes to the sepsis syndrome." (PMID 28484719, 2017). "In this study, we report that 1,25(OH)2D3 treatment has beneficial effects and improves the survival rate in LPS-induced mouse sepsis model by blocking the secretion of high-mobility group box 1 (HMGB1), a key late regulator of sepsis." (PMID 29085368, 2017). "Nuclear protein high mobility group box protein 1 (HMGB1) is released following cell death and is a late mediator in sepsis pathogenesis." (PMID 28724977, 2017). "Active secretion occurs when HMGB-1 is actively released extracellularly from the stimulation of tumour necrosis factor-α, interferon-γ, and other inflammatory mediators in sepsis." (PMID 27247778, 2016). "HMGB1 also contributes to renal ischemia reperfusion injury, sepsis-induced kidney injury and severe acute pancreatitis related kidney injury." (PMID 27980458, 2016). "The strong pro-inflammatory role of HMGB1 has been shown in autoimmune diseases, trauma, sepsis, and bacterial pneumonia." (PMID 27434276, 2016). "HMGB1, another well-characterized pleiotropic cytokine, is a crucial late mediator of mortality in sepsis." (PMID 27009867, 2016). "The high mobilitygroup box 1 (HMGB1) protein plays an important role as a late mediator of sepsis andALI." (PMID 26648090, 2016). "As demonstrated in a recent study, ethyl pyruvate treatment showed a significant decrease in HMGB1 levels that was correlated with improved lethality in the mice with sepsis." (PMID 27026909, 2016).
Sepsis (continued). "HMGB1 releasing elicits a severe inflammatory response, leading to tissue injury, and lethal sepsis in several infectious diseases." (PMID 27929533, 2016). "Pharmacological inhibition of the PKM2–EIF2AK2 pathway reduced the release of both early (for example, IL-1β) and late (for example, HMGB1) proinflammatory mediators and protected animals against lethal sepsis." (PMID 27779186, 2016). "Inflammatory cytokines (TNF-α, HMGB1, IL-1β, IL-6, and IL-8) were increased while anti-inflammatory cytokines (IL-10) were decreased, in serum and lung in sepsis patients." (PMID 27413421, 2016). "HMGB1 was initially recognized as a DNA-binding protein widespread in the mammal eukaryotic cell nucleus until the discovery that HMGB1 serves as a late inflammatory cytokine in the progress of sepsis and endotoxaemia in 1999." (PMID 27800496, 2016). "The stress responsive heme oxygenase (HO-1) 1 decreases serum HMGB1 levels in animal models of sepsis and improves patient survival, thereby demonstrating its therapeutic potential in sepsis." (PMID 27716835, 2016). "Vascular endothelial growth factor and HMGB1 elevations in sepsis were demonstrated to be amplified by CKD in CKD-sepsis animal models." (PMID 27011788, 2016). "HMGB1 increases in blood approximately 16 h after infection in models of sepsis and persists for several days during which mice die." (PMID 25787746, 2016). "Our previous study also showed that HO-1 can improve survival and decrease serum HMGB1 levels in a mouse model of sepsis, further indicating the beneficial effects of HO-1 in inflammatory disorders." (PMID 27716835, 2016). "Inflammatory cytokines like TNF-α and HMGB1 were increased, while anti-inflammatory cytokines like IL-10 were decreased in sepsis." (PMID 27413421, 2016). "PDF can effectively eliminate more large pivotal inflammatory mediators of TNFα and HMGB1 and improve the sepsis-related gut barrier dysfunction and apoptosis of lymphocyte, and meanwhile, it benefits the circulation function and prolong the survival time." (PMID 27682607, 2016). "Further investigation is necessary to elucidate the role of HMGB1 in human sepsis complicated with CKD." (PMID 27011788, 2016). "In this study, we only measured serum TNF-α levels (at 1 h) as the representative cytokine for the early stage of sepsis and HMGB1 levels (at 24 h) for the late stage." (PMID 27716835, 2016). "Clinical investigations have shown that the presence of autoantibodies to HMGB1 are beneficial to sepsis patients." (PMID 27537498, 2016). "It is very gratifying to see that PDF effectively attenuated the TNF-α and HMGB1 levels in serum and also improved apoptosis of lymphocyte and sepsis-related gut barrier injury." (PMID 27682607, 2016). "Inflammatory cytokines (TNF-α, IL-6, and HMGB1) were increased, while anti-inflammatory cytokines (IL-10) were decreased in sepsis." (PMID 27413421, 2016). "HMGB1, a potent late proinflammatory mediator in sepsis, also increased permeability of cultured epithelial monolayers in vitro and murine ileal mucosa in vivo." (PMID 27682607, 2016). "HMGB1 has been reported involved in various pathologies that include ischemia/reperfusion-induced injuries in hepatic cells and myocardial cells, sepsis-induced myocardial dysfunction, acute lung inflammation, and arthritis." (PMID 27821807, 2016). "It must be addressed that the CKD condition caused mild but significant VEGF and HMGB1 elevations before sepsis induction and acute complete loss of renal function by BNx also caused VEGF and HMGB1 elevations in blood." (PMID 27011788, 2016). "In previous study, we demonstrated that changes in plasma HMGB-1 and mtDNA levels in patients with severe trauma and sepsis." (PMID 27247778, 2016). "For example, in sepsis and endotoxemia, HMGB1 levels plateaued between 24 to 36 hours after infection." (PMID 27792814, 2016). "We have previously reported that PI3Kγ plays a role in the regulation of cardiomyocyte HMGB1 production in sepsis." (PMID 27821807, 2016).
Sepsis (continued). "During sepsis, high-mobility group box-1 (HMGB1), a DNA- and heparin-binding protein with pro-inflammatory activity, enhances and prolongs inflammatory processes." (PMID 27012162, 2016). "Experimental data suggest that secretion of HMGB1 and several inflammatory cytokines (e.g. IL-18) in severe sepsis is inflammasome-dependent." (PMID 27434276, 2016). "Acteoside was also found to inhibit the high-mobility group box 1 (HMGB1) release in vitro and decrease serum and lung HMGB1 levels in CLP-induced sepsis in vivo, presumably related to the binding of C5a to the C5L2 protein, a closest homology with C5aR." (PMID 27499603, 2016). "Survivors of sepsis models show prolonged increases in serum HMGB1 and cognitive deficits that are blunted with HMGB1 antibody treatment." (PMID 25787746, 2016). "Previously, it was demonstrated that HMGB1 and S100A12 are released in patients with severe sepsis and HMGB1 in mice with experimentally induced abdominal sepsis." (PMID 26824892, 2016). "On the other hand, HMGB1 has been identified as a late mediator of sepsis and plays a critical role in endothelial cell barrier disruption by rearranging the actin cytoskeleton into a contractile phenotype." (PMID 27716835, 2016). "HMGB1 is a cytokine mediator of lethal systemic inflammatory conditions like sepsis, whereas HO-1 protects against sepsis-induced lung injury by blocking the release of HMGB1." (PMID 27716835, 2016). "Using a mouse model of sepsis, we previously demonstrated that HMGB1 expression in cardiomyocytes is modulated by PI3Kγ." (PMID 27821807, 2016). "Survivors of sepsis show prolonged increases in serum HMGB1 and cognitive deficits that can be prevented with HMGB1-antibody treatment." (PMID 26695754, 2015). "In animal models of sepsis, HMGB1-neutralizing antibodies or inhibitors can rescue mice from the lethality, particularly if administered in a delayed manner to preserve the potentially beneficial early PAMPs-mediated inflammatory responses." (PMID 26257917, 2015). "Considering the late and prolonged kinetics of HMGB1 accumulation in experimental sepsis, the first dose of HMGB1 inhibitors was administered in a delayed fashion 24 h after the onset of sepsis." (PMID 26257917, 2015). "It has also been shown that blockade of IL-6 and HMGB1 increases the survival of septic animals with established sepsis." (PMID 25930108, 2015). "In acute inflammatory events like SIRS or sepsis, HMGB1 plays an important role in the course of systemic immune response." (PMID 26854151, 2015). "Breast cancer/sepsis monocytes also displayed higher expression of HMGB1 as well as several matrix metalloproteinases, which have previously been shown to be involved in the reprogramming of monocytes and metastatic/angiogenic processes respectively." (PMID 25992611, 2015). "For instance, in animal models of endotoxemia or sepsis (induced by cecal ligation and puncture, CLP), HMGB1-neutralizing antibodies improve survival and rescue rodents from lethal sepsis even if given at 24 h after CLP." (PMID 25821489, 2015). "Of particular interest is the possibility that the acetylation-dependent interaction of SIRT1 and HMGB1 participates in the pathophysiology of sepsis." (PMID 26522327, 2015). "More recently, we observed that the resveratrol-mediated inhibition of HMGB1 nucleo-cytoplasmic translation in sepsis-induced liver injury depends on SIRT1-mediated deacetylation." (PMID 26525891, 2015). "HMGB1 has been described as an early proinflammatory factor and plays a crucial role in many pathophysiological processes, such as sepsis, rheumatoid arthritis and liver injury." (PMID 25884983, 2015). "As a key late-phase proinflammatory cytokine, HMGB-1 participates in the physiopathological course of sepsis and has become an important target for the prevention and treatment of sepsis." (PMID 25944988, 2015).
Sepsis (continued). "This late appearance of circulating HMGB1 parallels with the onset of animal lethality from endotoxemia or sepsis and distinguishes itself from TNF and other early proinflammatory cytokines." (PMID 26257917, 2015). "HMGB-1 is a late mediator of lethal systemic inflammation in animal models of cytokine-mediated sepsis." (PMID 26579229, 2015). "The phylum Firmicutes and the families Streptococcaceae and Lactobacillaceae were negatively correlated with many inflammatory markers of sepsis progression, such as IL-6, IL-18, HMGB1 and CRP." (PMID 25881250, 2015). "In murine models of endotoxemia and CLP-sepsis, HMGB1 is first detected in the circulation 8 h after the disease onset and is subsequently increased to plateau levels from 16 to 32 h." (PMID 26257917, 2015). "Unfortunately, this simple intervention was ineffective in reducing septic mortality, prompting the search for other HMGB1-targeting agents for treating sepsis in humans." (PMID 26257917, 2015). "Release of HMGB1 by splenic MΦs occurs upon extensive splenic cell apoptosis, a feature commonly observed during sepsis." (PMID 26441984, 2015). "HMGB1 is a late mediator of sepsis released by macrophages/monocytes in response to pathogen-associated molecular patterns." (PMID 26420913, 2015). "Evidence has shown that HMGB1 increases the hyperpermeability of endothelial cells in sepsis and acute lung inflammation." (PMID 25884983, 2015). "Numerous cytokines and inflammatory mediators, including IL-1, IL-6, IL-12 and TNF-α, are documented to be released in the early phase of sepsis, while HMGB1 is released at the late phase." (PMID 25930108, 2015). "In the past ten years, only a minority of research focused on observing the predictive role of HMGB-1 on disease severity and prognosis in patients with sepsis, including different findings." (PMID 25944988, 2015). "The HMGB1 protein is an endogenous ligand that plays an important role inthis process and is directly related to sepsis and increased mortality." (PMID 26735599, 2015). "Necrostatin 1, an inhibitor of necroptosis, inhibits ROS accumulation and HMGB1 release/activity in experimental animal models of sepsis and I/R injury." (PMID 25904867, 2015). "In vivo, HMGB1 is first detectable in the circulation 8 h after the onset of lethal endotoxemia and sepsis, subsequently increasing to plateau levels from 16 to 32 h." (PMID 25904867, 2015). "Anti-HMGB1 neutralizing monoclonal antibodies improve the memory deficit observed in experimental sepsis, although the mechanism of neuroprotection behind this protective effect is still under investigation." (PMID 25698933, 2015). "In a more clinically relevant CLP-induced sepsis, the delayed administration of HMGB1-specific neutralizing antibodies beginning 24 h after CLP dose-dependently rescued rodents from lethal sepsis." (PMID 26257917, 2015). "Considering the late and prolonged kinetics of HMGB1 accumulation in experimental sepsis, the first dose of HMGB1 inhibitors was given in a delayed fashion, 24 h after the onset of sepsis." (PMID 25821489, 2015). "C5L2 stimulation by C5a caused release from cells of the protein high mobility group box 1 (HMGB1) both in vitro and in vivo and enhanced pathology in sepsis models." (PMID 26420913, 2015). "Antioxidants such as quercetin, edaravone, epigallocatechin gallate, and resveratrol significantly inhibit HMGB1 release in animal models of sepsis, suggesting that oxidative stress mediates HMGB1 secretion during infection." (PMID 25904867, 2015). "Since TM binds to HMGB-1 and promotes its degradation and inactivation in sepsis, we measured HMGB-1 mRNA and protein expressions in the lung." (PMID 25705415, 2014). "Subsequently, elevated levels of HMGB1 have been readily detectable in circulation of patients with severe sepsis and septic shock." (PMID 24524027, 2014).